TRIM67 (tripartite motif containing 67)
Diseases named in the same sentence as TRIM67 in open-access papers (continued):
Sharing a sentence is not in itself a finding about the gene and the disease.
Cerebral ischemia (1 paper, 2023). Restriction of arterial blood supply to the brain associated with insufficient oxygenation to support the metabolic requirements of the tissue. "Importantly, we found that TRIM67 overexpression significantly alleviated brain damage and cognitive deficits caused by cerebral ischemia‒reperfusion injury and decreased neuroinflammation and neuronal apoptosis." (PMID 37248543, 2023). "A mechanistic study showed that TRIM67 bound to IκBα, reduced K48-linked ubiquitination and increased K63-linked ubiquitination, thereby inhibiting its degradation and promoting the stability of IκBα, ultimately inhibiting NF-κB activity after cerebral ischemia." (PMID 37248543, 2023). "In this study, we observed that TRIM67 expression was significantly downregulated after cerebral ischemia‒reperfusion injury." (PMID 37248543, 2023). "The mouse peri-infarct hippocampus, cortex and striatum were extracted, and RT-qPCR analysis revealed that the level of Trim67 mRNA showed a continuous decrease and reached a plateau over 24 h after cerebral ischemia‒reperfusion injury." (PMID 37248543, 2023). "Overall, these results suggest that TRIM67 upregulation ameliorated the cognitive function injury induced by cerebral ischemia‒reperfusion injury." (PMID 37248543, 2023). "Collectively, these results indicate that the expression level of TRIM67 was reduced after cerebral ischemia‒reperfusion injury." (PMID 37248543, 2023). "RT-qPCR analysis revealed that cerebral ischemia‒reperfusion injury dramatically increased the mRNA levels of proinflammatory cytokines and chemokines, which were inhibited by TRIM67 upregulation." (PMID 37248543, 2023). "Tripartite motif-containing 67 (TRIM67) plays a crucial role in the control of inflammatory disease and pathogen infection-induced inflammation; however, the role of TRIM67 in cerebral ischemia‒reperfusion injury remains poorly understood." (PMID 37248543, 2023). "Overall, our data indicate that TRIM67 decreases inflammatory markers in brain tissue following cerebral ischemia‒reperfusion injury." (PMID 37248543, 2023). "In our work, we further revealed that TRIM67 is a neuroprotective molecule against cerebral ischemia‒reperfusion injury." (PMID 37248543, 2023). "We then examined the impact of TRIM67 on cognitive impairments following cerebral ischemia‒reperfusion injury." (PMID 37248543, 2023). "Our in vivo studies suggested that TRIM67 upregulation improved neurofunction and cognitive function against cerebral ischemia‒reperfusion injury." (PMID 37248543, 2023). "Interestingly, TRIM67 upregulation alleviated neuroinflammation and cell death after cerebral ischemia‒reperfusion injury in MCAO/R mice." (PMID 37248543, 2023). "The results demonstrated that cerebral ischemia‒reperfusion injury greatly increased the expression levels of phosphorylated IKKα/β (Ser176/180), IκBα (Ser32/36), and p65 (Ser536), which was considerably reversed by TRIM67 overexpression." (PMID 37248543, 2023). "Together, these data showed a previously undefined role for TRIM67 in cerebral ischemia‒reperfusion injury and suggested that TRIM67/IκBα signaling might be a potential therapeutic target for ischemic stroke treatment." (PMID 37248543, 2023). "Furthermore, by limiting the inflammatory response and enhancing neuronal survival, overexpression of TRIM67 dramatically decreased cerebral ischemia‒reperfusion injury in MCAO/R-challenged mice and OGD/R-stimulated cells." (PMID 37248543, 2023). "To explore the function of TRIM67 in cerebral ischemia‒reperfusion injury, we first detected whether TRIM67 expression was altered in vivo and in vitro." (PMID 37248543, 2023). "On the other hand, systemically administration with an agonist which could selectively upregulate TRIM67 enzyme activity or enhance its interaction with IκBα may provide protective effects against cerebral ischemia–reperfusion injury." (PMID 37248543, 2023).
Cerebral ischemia (continued). "Based on the findings of the in vivo and in vitro tests, we next studied whether TRIM67 upregulation could protect mice against cerebral ischemia‒reperfusion injury in vivo." (PMID 37248543, 2023). "In addition, we examined the role of TRIM67 in cerebral ischemia‒reperfusion injury by extensive overexpression but did not specify which cells were involved." (PMID 37248543, 2023).
Hepatic fibrosis (1 paper, 2022). The presence of excessive fibrous connective tissue in the liver. "Besides, the hepatic expressions of TIMP1 and TGFβ that related to hepatic fibrosis were induced by a high-fat diet in TRIM67 WT mice but not in TRIM67 KO mice." (PMID 35806477, 2022).
hypospadias (1 paper, 2022). Hypospadias is the displacement of the urethral meatus on the ventrum of the penis. "In the cohort of sporadic patients, we identified two additional variants in p38 MAPK signaling-related genes (TRIM67 and DAB2IP) potentially associated with hypospadias." (PMID 35606856, 2022).
ischemic stroke (1 paper, 2023). A stroke disorder caused by obstruction of blood flow to the brain, due to thrombotic (local blood clot formation) or embolic (due to a blood clot or other material traveling from another site) event. "However, the significance and underlying mechanisms of NF-κB regulation of TRIM67 are not fully understood in ischemic stroke." (PMID 37248543, 2023). "An in vivo transient focal cerebral ischemia‒reperfusion injury model and in vitro OGD/R-induced damage models were utilized in this study to determine the effects of TRIM67 as a neuroprotective factor against ischemic stroke." (PMID 37248543, 2023). "Meanwhile, proteomic analysis found that TRIM67 expression dramatically decreases following stroke, implying that it might be involved in ischemic stroke." (PMID 37248543, 2023). "More notably, prior research revealed that TRIM67 was markedly decreased after ischemic stroke and could inhibit NF-κB activation and lessen the release of inflammatory components, hence having a certain anti-inflammatory impact." (PMID 37248543, 2023). "Taken together, this study demonstrated a previously unidentified mechanism whereby TRIM67 regulates neuroinflammation and neuronal apoptosis and strongly indicates that upregulation of TRIM67 may provide therapeutic benefits for ischemic stroke." (PMID 37248543, 2023). "Therefore, maintaining TRIM67 expression might constitute a promising therapeutic target for the treatment of ischemic stroke." (PMID 37248543, 2023).
neuroblastoma (1 paper, 2024). Neuroblastoma (NB) is the most common solid, extracranial childhood tumor. "For example, knockdown of TRIM67 in immortalized neuroblastoma cells reduces neurite formation." (PMID 38495584, 2024). "Interestingly, previous work showed TRIM67 ubiquitinates Protein kinase C substrate 80K-H (80K-H) in the Ras pathway and reducing TRIM67 levels by siRNA increased Ras activity in a neuroblastoma cell line." (PMID 38495584, 2024).
Salmonella Infections (1 paper, 2025). Infections with bacteria of the genus SALMONELLA. "The conclusions of this study need to be further explored in the clinic and in multiple animal models to explore TRIM67-targeted therapeutic approaches against Salmonella infections." (PMID 40572155, 2025).
tumor (17 papers, 2020 to 2025). "In this study, TRIM67 was associated with tumor microcalcification, and ultrasonography may reflect changes in TRIM67 to some extent by monitoring the status of microcalcifications." (PMID 35795796, 2022). "Our previous study revealed a relationship between TRIM67 expression and carcinogenesis, showing that TRIM67 expression is linked to p-TNM stage, lymph node metastasis, tumour size, cancer cell differentiation, and poor prognosis." (PMID 38434968, 2024). "We found that xenograft tumour weight and volume were positively affected by variations in TRIM67 expression in these cells." (PMID 38434968, 2024). "The results showed that the model had the lowest RMSE when six variables (stage, TRIM67, tumor size, N, age, and HER2 status) were included in the SVM model." (PMID 35795796, 2022). "The general patient characteristics, the ultrasonographic information, the postoperative pathological information, and the predictive power of TRIM67 in tumor metastasis were assessed using SVM–RFE." (PMID 35795796, 2022). "TRIM67 was involved in neuroprotective effects and tumor processes, has been reported as a potential target to inhibit CRC metastasis." (PMID 35794546, 2022). "However, the results appeared to imply that a higher blood flow grading, positive lymph node metastasis prediction, and larger tumor size correlated with a higher TRIM67 expression." (PMID 35795796, 2022). "In addition, normal and tumor tissues showed different TRIM67 expression levels." (PMID 35795796, 2022). "TRIM67 overexpression, which may act like an oncogene, was reported to correlate with increased tumor growth, augmented tumor volume, elevated vimentin expression at tumor margins, and decreased overall survival in patient-derived oligodendroglioma-orthotopic implanted mice." (PMID 40426960, 2025). "The study results revealed that six variables [stage, TRIM67, tumor size, regional lymph node staging (N), age, and HER2 status] were suitable predictors of tumor metastasis by applying support vector machine–recursive feature elimination." (PMID 35795796, 2022). "Although without an established role in the context of ALT, TRIM67 has been indicated as a tumor suppressor gene in other malignancies." (PMID 38136279, 2023). "Interestingly, several are suggested to have tumor suppressor roles (FOXO3, TRIM67, UHRF2, CHD6)." (PMID 36008825, 2022).
cancer (7 papers, 2020 to 2024). A tumor composed of atypical neoplastic, often pleomorphic cells that invade other tissues. "Investigating the upstream regulators of TRIM67, such as microRNAs or transcription factors, may provide insights into the molecular mechanisms underlying its oncogenic role in cancer." (PMID 38434968, 2024). "TRIM67 is involved in cancer progression, neuritogenesis, and axonal guidance, as well as brain development and cognitive function." (PMID 38979475, 2024). "The current research on TRIM67 is very limited, most of which focuses on its role in cancer and inflammation." (PMID 37686246, 2023). "Among the 54 cancer-related genes, DGKG, MPND, NPIPB5, PRR21, SGSM1, and TRIM67 displayed frameshift mutations." (PMID 34104084, 2021). "Exploring the signalling pathways and molecular interactions that regulate the expression and function of TRIM67 may also reveal novel therapeutic targets for cancer treatment." (PMID 38434968, 2024). "Given the widespread involvement of the Notch pathway in cancer biology, TRIM67 may also play a role in other malignancies, such as breast cancer and leukaemia." (PMID 38434968, 2024). "Moreover, it is worthwhile to investigate the potential roles of TRIM67 and the Notch pathway in other types of cancer." (PMID 38434968, 2024). "Interestingly, TRIM67 is also involved in regulating the proliferation of cancer cells, and plays various roles in different cancers." (PMID 37686246, 2023). "In addition, the present study revealed 6 cancer-related genes, DGKG, MPND, NPIPB5, PRR21, SGSM1, and TRIM67, which showed novel frameshift mutations." (PMID 34104084, 2021). "To predict the cancer-promoting characteristics and prognosis of TNBC using the combination of the four genes, we calculated risk coefficients for co-expression integration and constructed a risk model with the following formula: risk score = 2*TBC1D24 + 1*TRIM67 + 1*QRSL1 + 1.8*ZDHHC9." (PMID 37875591, 2023). "Furthermore, it is important to understand the regulation and expression of TRIM67 and its interaction with DLK1 in NSCLC and other cancers." (PMID 38434968, 2024). "The Notch pathway is involved in the development of several cancers by influencing the expression of EMT-related proteins and other factors found to be altered by TRIM67 modulation; therefore, we examined whether TRIM67 is involved in the regulation of Notch signaling in NSCLC cells." (PMID 31956370, 2020). "Additionally, we detected the expression of TRIM67 in NSCLC tissues and cell lines by immunohistochemistry and western blotting and altered the expression of TRIM67 in NSCLC cells to study the variations of the cancer-related phenotype and determine its role in NSCLC." (PMID 31956370, 2020).
infection (6 papers, 2021 to 2025). The state of being infected such as from the introduction of a foreign agent such as serum, vaccine, antigenic substance or organism. "In summary, our findings revealed that TRIM67 function as a novel negative regulator of NF-κB signaling pathway, implying TRIM67 might exert an important role in regulation of inflammation disease and pathogen infection caused inflammation." (PMID 35273593, 2022). "Further studies revealed that TRIM67 knockout inhibited M1 polarization of macrophages in MLNs during infection." (PMID 40572155, 2025). "After infection, the expression of TRIM67 was significantly upregulated in mouse ileum, colon, mesenteric lymph nodes (MLNs), and peritoneal macrophages (PMs), suggesting its involvement in infection regulation." (PMID 40572155, 2025). "On day 3 post-infection, qRT-PCR and Western blotting were employed to evaluate TRIM67 mRNA and protein expression levels in the ileum, colon, and MLN, which are the primary sites of S. Typhimurium colonization." (PMID 40572155, 2025). "First, AAV-TRIM67 infection efficiency in brain tissue was validated by western blotting and RT-qPCR, revealing that both the mRNA and protein levels of TRIM67 were enhanced in mice treated with AAV-TRIM67 compared to vector-treated animals." (PMID 37248543, 2023). "In this study, we showed that TRIM67 deficiency significantly inhibited the recruitment and expansion of macrophages after infection, although it did not affect the number of colonic macrophages at homeostasis." (PMID 40572155, 2025). "By 12 h post-infection, bacterial loads in PMs from the KO group were significantly higher than in the WT group, consistent with in vivo observations, indicating that TRIM67 regulates macrophage-mediated S. Typhimurium clearance." (PMID 40572155, 2025). "In the present study, we found that intestinal NLRP3 expression was significantly upregulated after infection in wild-type mice, whereas TRIM67 deletion inhibited this process, resulting in reduced caspase-1 activity and decreased pro-inflammatory cytokine release." (PMID 40572155, 2025). "Together, these results demonstrate that TRIM67 knockout suppresses infection-induced macrophage recruitment and M1 polarization without affecting leukocyte numbers." (PMID 40572155, 2025). "TRIMs specific to the infection (TRIM59 for P. aeruginosa, TRIM67 for Chlamydia spp)." (PMID 37686095, 2023).
metabolic disease (2 papers, 2022). A congenital disorder (due to inherited enzyme abnormality) or acquired (due to failure of a metabolically important organ) disorder resulting from an abnormal metabolic process. "In this study, we show that TRIM67 in the hypothalamus was responsive to body-energy homeostasis whilst a deficiency of TRIM67 exacerbated metabolic disorders in high-fat-diet-induced obese mice." (PMID 36012700, 2022).
TRIM67 also shares sentences with these, for which no sentence is quoted: inflammation (2 papers); Alzheimer disease (1); Autoimmunity (1); bipolar disorder (1); Cognitive impairment (1); colon cancer (1); gastrointestinal infection (1); glioblastoma (1); Hepatic steatosis (1); Hypertension (1); leukemia (1); Lipedema (1); lipid metabolism disorders (1); major depression (1); metastatic tumors (1); muscular dystrophy (1); neurodegenerative disease (1); neurologic disorders (1); pancreatic cancer (1); Parkinson disease (1); schizophrenia (1); steatosis (1).